CUL4B (cullin 4B)
Diseases named in the same sentence as CUL4B in open-access papers (continued):
Sharing a sentence is not in itself a finding about the gene and the disease.
osteosarcoma (continued). "The NF‐κB transcription factor has five subunits, and we tested their abilities to regulate CUL4B expression in osteosarcoma cells." (PMID 29377600, 2018). "Based on our examination results in 54 osteosarcoma patients, it is possible that CUL4B levels affect tumor survival." (PMID 29377600, 2018). "Given that CUL4B was induced at the mRNA and protein levels, it is highly possible that CUL4B was regulated by a transcription factor in osteosarcoma cells." (PMID 29377600, 2018). "Our recent study suggests that CUL4B associates with DDB1, RBX1, and DCAF11 to form a unique CRL4BDCAF11 E3 complex in human osteosarcoma cells, and this E3 ligase can specifically target p21Cip1 for degradation, thereby regulating cell cycle progression." (PMID 29377600, 2018). "Consistent with the phenotypes of osteosarcoma cells, the up‐regulation of RelA, RelB, c‐Rel, and CUL4B in hFOB1.19 cells also led to increased colony formation and increased invasion." (PMID 29377600, 2018). "CUL4B mRNA and protein were both specifically overexpressed in these human osteosarcoma cell lines, although CUL4A also exhibited a slight induction under the same conditions." (PMID 28446751, 2017). "As expected, osteosarcoma cells expressing lower levels of CUL4B, DDB1 or DCAF11 exhibited dramatically higher percentages of cells in S phase." (PMID 28446751, 2017). "Our previous work revealed that the CUL4B gene was overexpressed in the osteosarcoma cell line Saos-226." (PMID 28446751, 2017). "Our results provide evidence for a potential new DCAF11 pathway in which DCAF11 associates with CUL4B and DDB1 to target p21 for proteolysis in human osteosarcoma cells." (PMID 28446751, 2017). "Here, we demonstrated that CUL4B forms an E3 ligase with RBX1 (RING-box 1), DDB1 (DNA damage binding protein 1), and DCAF11 (DDB1 and CUL4 associated factor 11) in human osteosarcoma cells." (PMID 28446751, 2017). "Given the similar CUL4B expression levels in these four osteosarcoma cell lines, we performed the following experiments in only U2OS and/or Saos-2 cells." (PMID 28446751, 2017). "To illuminate the molecular function of CUL4B, especially to determine interacting proteins and to identify the substrates of CRL4B E3 ligase in osteosarcoma cells, we first confirmed interactions between CUL4B and RBX1 or DDB1 in vivo and in vitro." (PMID 28446751, 2017). "Quantitative RT-PCR (qRT-PCR) analysis indicated that CUL4B mRNA levels were specifically upregulated (~3–4-fold induction) in these four osteosarcoma cell lines compared with hFOB1.19 cells." (PMID 28446751, 2017). "Fortunately, we found that DCAF11 had a similar expression pattern to CUL4B and was upregulated in different osteosarcoma cells." (PMID 28446751, 2017). "Our study offers insights into how CUL4B specifically functions in osteosarcoma cells and demonstrates that osteosarcoma cells have a unique CRL4BDCAF11 E3 ligase system that functions in the regulation of cell cycle progression." (PMID 28446751, 2017). "This suggests an oncogenic role for the NEDDylated CUL4B in osteosarcoma." (PMID 38534381, 2024). "Disturbing CUL4B expression could increase sensitivity to chemotherapy in lymphoblastoid cells, non-small-cell lung cancer cells, osteosarcoma and bladder cancer cells." (PMID 33869025, 2021). "Based on previous experimental results and our findings that CUL4B was overexpressed in osteosarcoma cells and cancerous tissues, we speculate that NF‐κB can specifically bind to the CUL4B promoter region and regulate its expression." (PMID 29377600, 2018). "In addition, we also determined the localization patterns of RelA, RelB, p52, and CUL4B in clinical samples from patient 4, who was diagnosed with osteosarcoma at MSTS stage IV based on the histopathological features." (PMID 29377600, 2018). "Additionally, the expression of CUL4A, a paralogue of CUL4B, was slightly increased (~1.5‐fold induction) in osteosarcoma cells compared to osteoblast cells." (PMID 29377600, 2018).
osteosarcoma (continued). "To determine whether CUL4B is specifically regulated by NF‐κB in osteosarcoma cells, we selected IL‐6, CXCL5, and CCR5 as representatives to monitor their expression in U2OS, MG63, Saos‐2, and HOS cells." (PMID 29377600, 2018). "Importantly, TNF‐α/NF‐κB signaling is activated in osteosarcoma cells, increasing the abundance of NF‐κB subunits in the nucleus, thereby activating the expression of CUL4B and regulating the ubiquitination of p21Cip1." (PMID 29377600, 2018). "Given that the mRNA and protein levels of CUL4B were up‐regulated in osteosarcoma cells and cancerous samples, we speculated that the increase of CUL4B protein level resulted from its mRNA induction." (PMID 29377600, 2018). "Importantly, these results provide an opportunity to target the TNF‐α/NF‐κB/CUL4B axis in treating osteosarcoma." (PMID 29377600, 2018). "Cullin 4B, a member of the Cullins, which serve as scaffolds to facilitate the assembly of E3 ligase complexes, is aberrantly expressed in many cancers, including osteosarcoma." (PMID 29377600, 2018). "Thus, we answered the two key questions, and our results reveal the important role of the TNF‐α/NF‐κB axis in the regulation of CUL4B expression and cell cycle progression in human osteosarcoma cells." (PMID 29377600, 2018). "Thus, the significant overexpression of CUL4B was frequently observed in the majority of the osteosarcoma tumors." (PMID 29377600, 2018). "Consistently, western blot (WB) analysis also indicated that the CUL4B protein was significantly induced (~3–4-fold induction) in all four osteosarcoma cell lines and that CUL4A was slightly overexpressed (~1.3–1.6-fold induction), whereas other Cullin family proteins were not." (PMID 28446751, 2017). "One limitation of our studies is that we did not screen for DCAFs that associate with CUL4B in osteosarcoma cells; instead, we only examined the expression of DCAF1, 4, 8, 11 and 15, and not the expression of other DCAFs." (PMID 28446751, 2017). "Our previous work also identified CUL4B overexpression in osteosarcoma cells through an unknown molecular mechanism." (PMID 28446751, 2017). "Our previous studies have indicated that CUL4B is upregulated in human osteosarcoma cells." (PMID 28446751, 2017). "miRNA-708 might halt osteogenic sarcoma progression through aiming for CUL4B." (PMID 34338146, 2021). "To validate this hypothesis, we selected a CUL4A-overexpression ovarian cell line SKOV3 and a CUL4B-overexpression osteosarcoma cell line Saos2 and evaluated their cell proliferation abilities in the conditions of 0, 0.2, 2 and 20 μM NSC1892 treatments, respectively." (PMID 32140073, 2020). "In addition, we found that the TNF‐α/NF‐κB/CUL4B axis was activated in osteosarcoma cells." (PMID 29377600, 2018). "Thus, CUL4B was considered to be specifically overexpressed in human osteosarcoma cells, possibly through an unknown transcriptional mechanism, which also indicated that CUL4B has a unique role in human osteosarcoma cells." (PMID 28446751, 2017). "The report illustrated that CUL4B activated Wnt/β-catenin signaling by protecting β-catenin from GSK3-mediated degradation and promoted proliferation of human osteosarcoma and hepatoma cells." (PMID 31675361, 2019). "Recently, we observed that CUL4B forms the CRL4BDCAF11 E3 ligase, which specifically ubiquitinates and degrades the cyclin‐dependent kinase (CDK) inhibitor p21Cip1 in human osteosarcoma cells." (PMID 29377600, 2018). "As expected, osteosarcoma cells expressing lower levels of TNFR1, TNFR1 + RelA, TNFR1 + RelB, TNFR1 + c‐RelA, CUL4B, and CUL4B + RelA; SPD304‐treated cells; and p21‐overexpressing cells exhibited dramatically higher percentages of cells in the S phase." (PMID 29377600, 2018). "In summary, our results demonstrate that CUL4B forms an E3 ligase with RBX1, DDB1 and DCAF11 to recognize p21 as a substrate in human osteosarcoma cells." (PMID 28446751, 2017).
osteosarcoma (continued). "Thus, CDK2 might be only a CUL4B-associated protein, and its down-regulation in osteosarcoma cells expressing lower CUL4B, DDB1 or DCAF11 might not be regulated by DCAF11 but might rather be regulated by p21 induction, as p21 is an inhibitor of CDK2." (PMID 28446751, 2017). "Interestingly, NSC1892 also showed promising cytotoxicity to decrease the growth of other CUL4A- or CUL4B-overexpressing tumor cells such as SKOV3 ovarian cells and Saos2 osteosarcoma cells." (PMID 32140073, 2020). "We have previously shown that CUL4B, but not the other Cullins, is up‐regulated in human osteosarcoma cells." (PMID 29377600, 2018). "In addition, the same amount of CUL4B-Flag protein pulled down much more DDB1 and RBX1 protein in U2OS and Saos-2 osteosarcoma cells than in hFOB1.19 cells, suggesting that DDB1 and RBX1 are also upregulated in osteosarcoma cells." (PMID 28446751, 2017). "Knocking down any component of the CRL4BDCAF11 complex, including CUL4B, DDB1 or DCAF11, using short hairpin RNAs (shRNAs) attenuated the ubiquitination level of p21Cip1, inhibited osteosarcoma cell proliferation, led to cell cycle arrest at S phase, and decreased colony formation rate." (PMID 28446751, 2017). "We also observed a significant decrease in CDK2 levels after down-regulation of CUL4B, DDB1 or DCAF11 in osteosarcoma cells, which raised the question of whether DCAF11 is responsible for the degradation of CDK2." (PMID 28446751, 2017). "To determine whether CUL4B can interact with RBX1 and DDB1 in osteosarcoma cells, we first constructed the pCDNA3-CUL4B-Flag vector, which we then transfected into hFOB1.19, U2OS and Saos-2 cells." (PMID 28446751, 2017). "Our previous work revealed that Cullin 4B (CUL4B), a critical component of the Cullin4B-RING E3 ligase complex (CRL4B), is overexpressed in human osteosarcoma cells through an unknown mechanism." (PMID 28446751, 2017). "The CUL4B-Flag immunocomplex from hFOB1.19, U2OS or Saos-2 cells pulled down DCAF4 and DCAF11, but not DCAF1, 8 and 15, indicating that these two DCAFs form complexes with CUL4 and DDB1 in osteosarcoma cells." (PMID 28446751, 2017). "In addition, the overexpression of CUL4B in these cells was able to significantly reverse their growth defects, further suggesting that the TNF‐α/NF‐κB axis mainly contributed to CUL4B expression in osteosarcoma cells." (PMID 29377600, 2018). "However, due to the limited information for the role of CUL4B in the pathogenesis of cancer including osteosarcoma, we do not know its clinical relevance." (PMID 29377600, 2018). "However, we did not assess whether only CUL4B expression, and not the expression of the other six Cullin genes, was upregulated in osteosarcoma cells." (PMID 28446751, 2017).
gastric cancer (10 papers, 2019 to 2025). A primary or metastatic malignant neoplasm involving the stomach. "Targeting HER2 expression with trastuzumab treatment partially reversed the malignant progression of gastric cancer caused by CUL4B overexpression." (PMID 40156167, 2025). "For example, CUL4B is overexpressed in gastric cancer, and its overexpression is associated with poor prognosis and lymph node metastasis." (PMID 35909905, 2022). "A preceding investigation has delineated that HER2 is a downstream target of CUL4B in gastric cancer." (PMID 40156167, 2025). "CUL4B promotes gastric cancer cell invasion and epithelial-mesenchymal transition in vitro as well as tumor development and metastasis in vivo." (PMID 35909905, 2022). "A further study of relationship between CUL4B and tumour staging found that the expression of CUL4B was significantly increased in advanced gastric cancer." (PMID 36385733, 2022). "In gastric carcinoma, CUL4B is upregulated and targeted by miR-381 and miR-489, and silencing of CUL4B inhibits the proliferation and migration of gastric cancer cells via the Wnt/β-catenin signaling pathway." (PMID 33324542, 2020). "CUL4B is upregulated in diverse solid tumours, such as gastric cancer, CRC and pancreatic cancer." (PMID 40156167, 2025). "Additionally, CUL4B has been shown to promote gastric cancer invasion and metastasis through the upregulation of HER2, indicating its broad involvement in the regulation of multiple cancer types via distinct mechanisms." (PMID 40203790, 2025). "MiR‐381 directly targets Cullin 4B (CUL4B), an oncogene overexpressed in various cancers, and downregulates the expression of β‐catenin as well as c‐MYC and cyclin D1 in gastric cancer cells." (PMID 35014178, 2022). "The regulation of EMT by the Wnt signaling pathway has been determined including Wnt5a, FOXP3, SERPINH1, CUL4B, and SUFU, which can be used in BLCA, gastric cancer, and pancreatic cancer." (PMID 34579753, 2021). "In gastric cancer cells, THAP7-AS1 specifically interacted with importin α1 and the nuclear localization signal region of cullin 4B (CUL4B) and mediated the entry of THAP7-AS1/CUL4B complex into the nucleus." (PMID 37069649, 2023).
lung carcinoma (9 papers, 2017 to 2025). "While we have embarked on a preliminary exploration of CUL4B’s influence on lung cancer and cisplatin, a deeper understanding of the underlying mechanisms remains to be further investigated." (PMID 38075690, 2023). "This influence of CUL4B on the lung cancer microenvironment might shed light on its association with adverse prognostic outcomes." (PMID 38075690, 2023). "Moreover, we explored the underlying effect of CUL4B on lung cancer cell apoptosis." (PMID 38075690, 2023). "Subsequently, we retrieved the IHC images of CUL4B from the HPA database, which further indicated heightened protein levels of CUL4B in lung cancer tissues." (PMID 38075690, 2023). "The results revealed that tumors originating from the injection of CUL4B knockdown lung cancer cells had significantly lower weights compared to those from the control cells." (PMID 38075690, 2023). "Subsequently, we conducted xenograft experiments in nude mice to investigate the effects of CUL4B on the proliferation of lung cancer cells in vivo." (PMID 38075690, 2023). "Meanwhile, in vitro experiments indicated can CUL4B significantly promote the proliferation, invasion and migration of lung cancer cells." (PMID 38075690, 2023). "Results showed that the inhibition of CUL4B can significantly promote the apoptosis of lung cancer cells." (PMID 38075690, 2023). "The results indicated that, in addition to pancreatic cancer, SIRT1 and CUL4B are also significantly upregulated in esophagus, stomach, rectum, liver, and lung carcinomas, compared with adjacent normal tissues." (PMID 34163012, 2021). "We found that CUL4B was upregulated in lung cancer tissues and contributes to proliferation, migration, and invasion of non‐small‐cell lung cancer (NSCLC) cells." (PMID 28164432, 2017). "This study shows that CUL4B is upregulated in human lung cancer tissues and contributes to proliferation, migration, and invasion of NSCLC cells." (PMID 28164432, 2017). "Taken together, our data highlight the important role of CUL4B in lung cancer progression and establish a complex, microRNA‐mediated regulation of CUL4B protein levels." (PMID 28164432, 2017). "miR‐194 was further shown to attenuate the malignant phenotype of lung cancer cells by downregulating CUL4B." (PMID 28164432, 2017). "The function of miR‐194 as a negative regulator of CUL4B has therapeutic implications in lung cancer." (PMID 28164432, 2017). "To gain insight into the mechanism by which CUL4B is upregulated in lung cancers, we examined the mRNA and protein levels of CUL4B in 30 paired specimens of lung cancer and adjacent normal tissues." (PMID 28164432, 2017). "Additionally, Ki67 staining results demonstrated that tumors from CUL4B knockdown lung cancer cells exhibited a lower proportion of Ki67-positive cells compared to the control group." (PMID 38075690, 2023). "Western blot and qPCR results indicated an upregulation of CUL4B in lung cancer cell lines." (PMID 38075690, 2023). "Furthermore, suppressing CUL4B expression led to a noticeable reduction in the IC50 value of cisplatin in lung cancer cells." (PMID 38075690, 2023). "Taken together, these data suggest that NCBP1 mediates, at least in part, the proliferation, migration and invasion characteristics, as well as EMT, in lung cancer cells, and that CUL4B may be a downstream mediator of the effects of NCBP1." (PMID 31448526, 2019). "Given that CUL4B is an important ubiquitination‐related molecule, along with the fact that NCBP1 promotes the proliferation, migration and wound healing ability of lung cancer cells, we attempted to elucidate the underlying regulatory mechanism of CUL4B mediated by NCBP1." (PMID 31448526, 2019). "In this research, we found that CUL4B expression correlated with that of NCBP1 in lung cancer tissue and in cancer cell lines, and cotransfection with CUL4B plasmids partially reversed the effects of NCBP1 silencing on lung cancer cell line proliferation, migration and wound invasion." (PMID 31448526, 2019).
lung carcinoma (continued). "Moreover, miR‐194 expression is negatively correlated with CUL4B protein levels in lung cancer tissues, and miR‐194 is epigenetically repressed by the CRL4B complex assembled by CUL4B." (PMID 28164432, 2017). "In this study, we investigated the role of CUL4B in lung cancer." (PMID 28164432, 2017). "Importantly, we demonstrated an important role of miR‐194 in the posttranscriptional regulation of CUL4B in lung cancer." (PMID 28164432, 2017). "Notably, CUL4B was found to be overexpressed in both lung cancer tissues and cells." (PMID 38075690, 2023). "Interestingly, NCBP1 is required for capped RNA synthesis and intracellular translation, and has recently been discovered to interact with NCBP3 to induce CUL4B expression, promote lung cancer cell growth, wound healing, migration, and epithelial-mesenchymal transition." (PMID 35982949, 2022). "Furthermore, we identified the specific roles of CUL4A and CUL4B in lung cancer." (PMID 32587774, 2020). "Additionally, CUL4B expression was negatively regulated by miR-101-3p in lung cancer." (PMID 33233664, 2020). "However, no corresponding changes in CUL4B mRNA levels were observed, suggesting that the upregulation of CUL4B in lung cancer may have occurred at posttranscriptional levels." (PMID 28164432, 2017). "CUL4B appears to have a similar function in MPM, lung cancer and ovarian cancer, and is correlated with poor prognosis." (PMID 39852534, 2025). "Using the TCGA data set, we found that expression of CUL4B mRNA was significantly correlated, albeit moderately, with that of NCBP1 in lung cancer tissue (r = .32; P < .0001)." (PMID 31448526, 2019). "To examine the role of CUL4B as a mediator of the action of NCBP1 in lung cancer, we measured the viability of lung cancer cell lines with various combinations of plasmid transfections." (PMID 31448526, 2019). "To further explore the relationship between NCBP1 and CUL4B expression, we measured CUL4B protein expression in lung cancer lines with and without overexpression or knockdown of NCBP1." (PMID 31448526, 2019).